CRP (C-reactive protein)
Diseases named in the same sentence as CRP in open-access papers (continued):
Sharing a sentence is not in itself a finding about the gene and the disease.
infection (continued). "Laboratory investigation results are also nonspecific, with elevated WBC and CRP suggesting inflammation and infection." (PMID 40772203, 2025). "pullorum infection significantly elevated (p < 0.05) the renal (CREA, UREA), hepatic (ALT, AST), immunological (IgG, IgM), and inflammatory (TNF-α, IL-6, SAA, CRP) parameters, as well as the expression of trefoil factor 3, Toll-like receptor 2, TNF-α, IL-1β, and IL-6." (PMID 41597538, 2025). "In the group without infection (n = 116), we performed a correlation analysis between serum CRP levels and early (D1) and late (D9) LBP and sCD-14 values." (PMID 39859200, 2025). "The increase in CRP and leucocytes were interpreted as non-infections, thus no antibiotic treatment was initiated." (PMID 40634779, 2025). "Besides, C-reactive protein (CRP), a highly sensitive inflammatory marker, exhibits elevated concentrations in response to the severity of infection." (PMID 40408044, 2025). "Adding health and lifestyle factors in Step 2 increased the explained variance to 16% (R2Δ = .012, p < .001), with BMI emerging as a significant positive predictor, and recent infection emerging as a significant negative predictor of CRP." (PMID 40823322, 2025). "In group I, PSP correlated strongly with PCT (r = 0.638; p < 0.008), but not with CRP, supporting its role as an infection-specific marker." (PMID 40217689, 2025). "Levels of erythrocyte sedimentation rate and C-reactive protein were assessed to rule out infection." (PMID 40104774, 2025). "Additionally, C-reactive protein (CRP), an acute-phase protein that rises rapidly in response to infections, trauma, or other stimuli, is also relevant in this context." (PMID 40078589, 2025). "Traditional methods, reliant on nonspecific clinical manifestations and limited biomarkers like C-reactive protein and procalcitonin, often fail to distinguish infection from non-infectious inflammation or capture disease heterogeneity." (PMID 41300910, 2025). "For women after CC surgery, especially of preventive aim, increased serum CRP and PCT levels from post-CC day 1 to day 3 may signal a potential postoperative infection, warranting close monitoring." (PMID 38992621, 2024). "An additional 23 guidelines acknowledged the role of SF as an acute phase reactant that can increase in the presence of inflammation and/or infection, though measurement of CRP or another inflammatory marker was not explicitly stated." (PMID 39125438, 2024). "Concentrations of C-reactive protein (CRP), procalcitonin (PCT), interleukin-6 (IL-6), and tumor necrosis factor-alpha (TNF-α) in plasma and bronchoalveolar lavage fluid (BALF) measured at 6 h after infection were notably higher than those at 54 h." (PMID 38323827, 2024). "In this study, since the appropriate surgical timing for CC focuses on the period before 28 weeks of gestation, the late increase in CRP is unlikely to impact its application in predicting infection after CC." (PMID 38992621, 2024). "Reimplantation can be scheduled for patients meeting specific criteria, including the absence of local signs or symptoms of infection as well as CRP levels and ESR that are normal or downloading." (PMID 38761247, 2024). "In our case, normal blood count and CRP of the neonates in combination with the absence of symptoms/signs of the disease as well as the negative rK39 test excluded the active infection of the two offspring." (PMID 38673673, 2024). "Serum C-reactive protein (CRP) level, erythrocyte sedimentation rate (ESR), and white blood cell (WBC) count are routine blood indicators used to assess postoperative infection as they represent inflammatory and anti-inflammatory factors in the serum of postoperative trauma." (PMID 38434200, 2024). "Due to the low positive rate of microbiological culture, we suggest treating as ONFH accompanied with septic hip when ESR and CRP significantly increase and MRI indicates infection, even if microbiological culture is negative." (PMID 38195515, 2024).
infection (continued). "Subphenotype C was associated with community-acquired SAB from an unknown source, with higher C-reactive protein (CRP) and with the presence of metastatic foci of infection." (PMID 38916975, 2024). "The levels of IL-6 were found also elevated in patients with infection than in patients without infection (t = 3.5, p = 0.0007), while the levels of Neu and CRP were similar in patients with inflammation of either infectious or non-infectious etiology." (PMID 39338437, 2024). "Ordinarily, the concentration of CRP in urine hovers around a range of 1–100 mg/mL, whereas in serum, it varies between 1 to 1000 mg/mL contingent upon the type of infection or the absence of inflammation." (PMID 39143107, 2024). "ESR and CRP are first-line screening markers of PJI in infection with high-virulence organisms and patients not on any antibiotics." (PMID 39493345, 2024). "IL-6 may be helpful in the earlier prediction of infection to some extent because it is elevated in infection before PCT and CRP." (PMID 38504206, 2024). "CRP was significantly different with highest levels in MDR infection followed by MDR colonisation and lowest in non-MDR at the time of the first SBT, as well as at the last measurement." (PMID 38317197, 2024). "It is worth noting that increased levels of CRP are found in various inflammation and infection processes, so it is not specific to IBD; thus, its use as a biomarker needs to be complemented with other, more specific diagnostic tests." (PMID 39000169, 2024). "Of the 52 reported episodes of infection, in 42 (14 CF, 28 BC) CRP was > 10 ug/mL, with/without positive blood culture, while in four episodes (2 CF, 2 BC) CRP was < 10 ug/mL and blood cultures negative/not performed." (PMID 38775927, 2024). "For protein-based biomarkers, notably CRP and PCT, a single determination has modest diagnostic performance in infection and does not reliably distinguish between bacterial and viral infection." (PMID 39020244, 2024). "Due to the amplification effect of proinflammatory cytokines such as interleukin (IL)-8 and IL-18, MRMP infection might elicit a persistent and intense immune response, with LDH being considered a more sensitive immunological marker than CRP." (PMID 39143259, 2024). "Several biomarkers such as C-reactive protein (CRP), interleukin 6 (IL-6), and procalcitonin (PCT) are widely used in clinical practice for the early diagnosis and prediction of clinical outcomes in patients with infection." (PMID 38892234, 2024). "We performed a systematic review and meta-analysis to evaluate the diagnostic accuracy of procalcitonin (PCT) and to compare it with C‐reactive protein (CRP) in adult non-neutropenic cancer patients with suspected infection." (PMID 38438974, 2024). "The serum infection/inflammation markers showed no statistical difference in CRP values among the pregnant participants." (PMID 39458089, 2024). "Acute phase proteins, including C-reactive protein (CRP), fibrinogen, haptoglobin, lipocalin-2, and serum amyloid As (SAAs), are plasma proteins that rapidly increase in blood levels, by 5- to 1,000-fold, in response to inflammation, infection, and trauma." (PMID 39210819, 2024). "While leukocytes, CRP, IL-6, and PCT are widely recognized as important markers of inflammation and infection, it is acknowledged that other cytokines and biomarkers may provide valuable insights into the effectiveness of hemoadsorption therapy." (PMID 39768616, 2024). "Several biomarkers derived from peripheral blood, such as the ESR, CRP, white blood cell (WBC) count, and leukocyte classification, can assist medical professionals in determining inflammatory status, severity of infection, and type of infection within the body." (PMID 38741113, 2024). "We observed that the LDNs and MDSC subsets were positively correlated with CRP and PCT levels, suggesting that they could also be potential infection biomarkers." (PMID 38609858, 2024).
infection (continued). "It is noteworthy that in addition to aspiration and evaluation of ESR and CRP, performing a staged procedure in terms of culture and removing hardware may be essential to decrease the post-THA infection rate." (PMID 38245744, 2024). "The third theme discusses the use of intermediate CRP levels (above the trial’s 5 mg/L cut-off) as an indicator of serious infection, as opposed to its intended role in the trial as a rule-out factor." (PMID 39691791, 2024). "Subsequent signs of infection, such as uterine tenderness, elevated WBP, CRP, and erythrocyte sedimentation rate, and fever, may require reintroduction of antibiotics." (PMID 38671355, 2024). "Additionally, the plasma half-life of PCT is 24 hours, while that of CRP is 19 hours, meaning PCT normalizes in the blood more quickly after the infection is resolved." (PMID 39618643, 2024). "However, after the initial three days of admission, investigating at least two weeks of the period of the disease, CRP and PCT demonstrated good predictive accuracy for infection." (PMID 38279274, 2024). "The predictive value of CRP and PCT for infection is poor within 72 h after hospital admission." (PMID 38279274, 2024). "It is recommended that the level of C-reactive protein be measured because a high level indicates the possibility of an ongoing infection, in which case the AAT test result should not be taken into account and the test should be repeated." (PMID 39661838, 2024). "No signs of infection were detected in any of the patients, and CRP levels spontaneously dropped to normal values within a few days." (PMID 39768440, 2024). "After admission, blood routine test showed white blood cells 10.96 × 109/L, neutrophil count 9.10 × 109/L, lymphocyte count 1.03 × 109/L, whole blood C-reactive protein (CRP) 28.66 mg/L, and procalcitonin (PCT) 0.245 ng/mL, and moxifloxacin was used for empiric anti-infection therapy." (PMID 39654192, 2024). "All had normal IG values, with of 8 (10%) had an increase in white blood count (>10,000/uL) and of 14 (14,8%) had hs-CRP > 3 mg/L, with no fever nor signs of infection." (PMID 39231181, 2024). "An international consensus meeting in 2018 on Orthopaedic infection mentioned that ESR and CRP alone should not be relied on to rule out infection." (PMID 39493345, 2024). "Our findings support the presence of induced systemic inflammation and mucosal injury during non-invasive ETEC infection, notably marked by an increase in CRP and SAAt with a decreased truncation pattern in SAA1.1 and Reg3a during the early infection phase in the SP group." (PMID 38430452, 2024). "The laboratory findings showed increased white blood cells, C-reactive protein (CRP), and erythrocyte sedimentation rate (ESR), indicating a possible infection and the cultures of the ulcerated lesion revealed a large amount of Enterobacter cloacae and Staphylococcus aureus colonies." (PMID 39659344, 2024). "CRP and PCT could exclude the infection probabilities in critical ill patients but the predictive performance was vulnerable to the impact of antibiotic utility." (PMID 38993672, 2024). "Specifically, CRP measurements within the first 48 hours post-symptom onset enhance test sensitivity, with normal CRP values indicating a 99% negative predictive value for infection." (PMID 39347186, 2024). "Overall, 12/15 patients (80%) showed intermittent elevated levels of acute phase reactants (SAA [n = 10; 67%], CRP [n = 2; 13%] and leucocytosis [n = 1; 7%]) without signs of infection." (PMID 38628041, 2024). "CRP is acknowledged to have a negative correlation with glomerular filtration rate, yet it remains a reliable predictor of infection in individuals with compromised renal function." (PMID 38667467, 2024). "Laboratory markers like CRP, urea, and creatinine were similar across both cohorts, consistent with their role as indicators of infection severity and renal involvement rather than recurrence-specific changes." (PMID 39334674, 2024).
infection (continued). "CRP is one of the most established and widely used nonspecific markers for inflammation and infection." (PMID 38293363, 2024). "Infection eradication was determined by the normalization of the C-reactive protein, erythrocyte sedimentation rate levels, or the absence of clinical infection symptoms." (PMID 39596762, 2024). "Procalcitonin is a biomarker increasingly used to differentiate between bacterial and non-bacterial courses of inflammation and/or infection, with higher sensitivity and specificity compared to CRP." (PMID 39057774, 2024). "Erythrocyte sedimentation rate (ESR) and C-reactive protein (CRP) must be done to rule out subclinical infection preoperatively." (PMID 38975433, 2024). "The elevation of CRP in DLBCL may result from higher disease activity, deeper and larger ulcer or occult infection." (PMID 38504190, 2024). "In the case we present, infection was ruled out as both inflammatory biomarkers (CRP and PCT) and microbiologic cultures were negative." (PMID 39238746, 2024). "After analysis, the differences in white blood cell count (WBC), proportion of monocytes (MONO), and C-reactive protein (CRP), procalcitonin (PCT), and aspartate aminotransferase (AST) levels were statistically significant after infection with different MP loads." (PMID 38655275, 2024). "In summary, we found strong associations between clinical response trajectories and both infection sources and different pathogen groups in patients with suspected BSI, with distinct CRP response patterns, reflecting normal, slow, and delayed or limited responses." (PMID 38599549, 2024). "Furthermore, our study provides additional details about the immunomodulatory effects of CSFV on the kinetics of CRP, TNF-α, and leukocyte sub-populations in pigs after infection with the CSFV strain Paderborn." (PMID 38393074, 2024). "Conversely, in patients with active infection that progressed during the post-decannulation period, the body temperature tended to gradually increase, and the fever lasted longer with higher CRP levels than in patients without active infection." (PMID 39797141, 2024). "CRP is an acute phase protein synthesized by hepatocytes when the body is exposed to inflammatory stimuli (e.g., infection or tissue injury) and is part of the nonspecific immune machinery." (PMID 38335409, 2024). "Nevertheless, the concentration of serum CRP is not specific enough to diagnose localized infection due to its presence in various noninfectious inflammatory processes as an acute-phase reactant." (PMID 38847648, 2024). "Due to faster and more effective adjustment of the anti-infection regimen, it was found that the changes in ESR, CRP, PaO2/FiO2, SOFA score, CURB-65 score and APACHE II score from admission to discharge were significantly higher than that in conventional group." (PMID 39621807, 2024). "Acute-phase proteins such as CRP and AGP increase during infection or inflammation." (PMID 39324337, 2024). "They examined whether changes in ESR, CRP, and synovial WBC counts between stages could predict infection resolution." (PMID 39493345, 2024). "Inflammatory markers, such as CRP and ESR, also tend to increase in the early stages, which can further complicate the diagnosis in pediatric patients, as these symptoms can mimic infection." (PMID 39445277, 2024). "The patient’s workup included consultation from multiple orthopaedic and general surgeons, CRP, erythrocyte sedimentatin rate, and imaging to rule out infection, fracture, aseptic loosening, and hernias." (PMID 39735212, 2024). "Although PCT is often postulated to have a higher prognostic value than CRP, PCT was not shown to be associated with 28-day all-cause mortality in 371 patients with signs of infection." (PMID 37204560, 2024). "Compared with CRP and PCT, IL-6 has a higher predictive value for postoperative infections." (PMID 38504206, 2024).
infection (continued). "In conclusion, for women undergoing CC surgery, an increase in serum CRP and PCT on post-CC day 1 to day 3 may be an early sign of postoperative infection." (PMID 38992621, 2024). "In both countries, some guidelines for the management of infections recommended using CRP, but not specifically CRP POCTs." (PMID 38504318, 2024). "The average value of CRP in the patients with infection was 117.5 mg/L; in patients without replacement infection, it was a CRP of 10.3 on average mg/L." (PMID 38337382, 2024). "Previous studies reported that CRP levels increased to ≥10 mg/dl on the 14th postoperative day in patients with post-ACLR infection, whereas in those with no complications, the levels remained below 5 mg/dl." (PMID 39539898, 2024). "Because of this delay, most participants in both countries felt that low levels of CRP were not useful to exclude severe infections." (PMID 38504318, 2024). "CRP is a non-specific acute-phase reactant produced by the liver in response to inflammation, infection, and tissue damage." (PMID 39696496, 2024). "While assessing the patient's condition after admission, the patient's Sequential Organ Failure Assessment (SOFA) score was 9 points, and elevated C-reactive protein (CRP) levels and white blood cell (WBC) counts were observed, indicating the presence of infection and inflammation." (PMID 39483585, 2024). "Contrary to the study design—where CRP is intended to rule out severe infections due to its higher specificity but lower sensitivity—they use CRP to rule them in." (PMID 39691791, 2024). "C-reactive protein (CRP) is a non-specific acute-phase reactant that is elevated during infection and inflammation." (PMID 39759701, 2024). "There were no signs of infection, with a C-reactive protein (CRP) of 9 mg/L, negative blood and spinal fluid cultures, as well as fecal and nasopharyngeal polymerase chain reaction tests." (PMID 39237896, 2024). "Of these, 584 patients were excluded for not having a diagnosis of infection during hospitalization, 78 patients for not having a confirmed diagnosis of oncological disease, and 47 patients for a lack of CRP measurements." (PMID 39272020, 2024). "Vitamin C may have immunomodulatory functions, such as the suppression of pro-inflammatory cytokines such as interleukin (IL)-6, tumor necrosis factor (TNF)-α, and C-reactive protein (CRP), and reduce oxidative stress, which are increased during infection." (PMID 38730366, 2024). "As for CRP, in the IAE group, CRP levels showed no statistic difference in the early anti‐infection (12–24 h) compared with baseline, and significantly decreased at 48 to 72 h (T3–T4)." (PMID 38967137, 2024). "Instead, they attempt to interpret CRP in relation to the presence or absence of a serious infection." (PMID 39691791, 2024). "In haematological patients, the increase of TTV load is closely associated with immune system activity and various infection indicators (such as ANC, CRP, PCT), consistent with previous research, indicating its potential as a biomarker for infection in haematological patients." (PMID 39044261, 2024). "WBC, NE and CRP counts were significantly higher in the mycoplasma-, bacteria-, fungal- and chlamydia-positive groups, compared to the infection-negative group (p < 0.05)." (PMID 38455965, 2024). "C-reactive protein (CRP) is a non-specific acute phase protein that is induced by IL-6, and is a sensitive systemic marker of inflammation, infection, and tissue ﻿damage." (PMID 38493133, 2024). "The patient should have stable inflammatory markers (eg, white blood cell count, ESR, and CRP) within normal reference ranges for at least 1 year, without clinical signs of infection such as ongoing pain or discharge from a prosthetic joint site." (PMID 38832929, 2024).